CD59 (CD59 molecule (CD59 blood group))
Diseases named in the same sentence as CD59 in open-access papers (continued):
Sharing a sentence is not in itself a finding about the gene and the disease.
preeclampsia (6 papers, 2014 to 2025). Preeclampsia is a hypertensive disorder of pregnancy that is characterized by new-onset hypertension with proteinuria presenting after 20 weeks of gestation, and depending on mild or severe forms may initially present with severe headache, visual disturbances, and hyperreflexia. "An observational case control study of preeclampsia with severe features also found that plasma levels of CD59 were elevated while urinary levels were reduced, relative to normotensive controls." (PMID 40777009, 2025). "Histones, integrins and CD59 glycoprotein were downregulated while the remaining were upregulated in preeclampsia." (PMID 25469110, 2014). "Although soluble (plasma) CD59 is less effective than its membrane-bound form, it may still contribute to systemic complement regulation in preeclampsia." (PMID 40777009, 2025). "However, in preeclampsia, placental deposition of C5b-9 is increased which may be due to increased complement activation or due to impaired regulation by CD59." (PMID 40777009, 2025). "In a study that measured placental mRNA expression of the complement regulatory proteins in preeclampsia at the time of delivery, a significant upregulation of CD55 and CD59 mRNA expression was observed." (PMID 26556948, 2015). "At the same time, in placental tissue in patients with preeclampsia, on the contrary, a significant decrease of regulatory cells CD4+, CD8+, CD14+, CD56+, CD59+, activation markers CD95+, as well as anti-inflammatory cytokine IL-10, growth factors VEGFR and IGF was detected." (PMID 40647643, 2025). "At the same time, in placental tissue in patients with preeclampsia, on the contrary, a significant decrease in regulatory cells CD4+, CD8+, CD14+, CD56+, CD59+, activation markers CD95+, as well as anti-inflammatory cytokine IL-10, growth factors VEGFR and IGF was detected." (PMID 40647643, 2025).
acute myocardial infarction (5 papers, 2016 to 2025). Necrosis of the myocardium, as a result of interruption of the blood supply to the area. "A soluble form of CD59 (sCD59) is present in various body fluids and is associated with cellular damage after acute myocardial infarction." (PMID 27215188, 2016). "This study aimed to observe the expression of CD59 in human heart and the relationship between C5b-9 deposition and CD59 in myocardial tissue specimens obtained at autopsy from patients who had died of myocardial infarction." (PMID 36732841, 2023). "In this study, H&E stained slides and fibronectin, CD59, cathepsin S, troponin T, desmin, and myoglobulin stained immunohistochemistry slides of 20 cases diagnosed with early myocardial infarction were retrospectively analyzed." (PMID 35371665, 2022). "The deposition of C5b-9 as an end-product of complement activation on cell membrane may lead to CD59 release during ischemia in patients with acute myocardial infarction." (PMID 36732841, 2023). "It has been shown that there is an increase in blood CD59 levels in acute myocardial infarction." (PMID 35371665, 2022). "In addition, the immunoblotting and immunofluorescence analysis revealed that the CD59 was observed in the sarcolemmal membranes of normal myocardium, but was lost or clearly diminished in infarcted areas during 1–14 days after the onset of myocardial infarction." (PMID 36732841, 2023).
cervical carcinoma (5 papers, 2014 to 2022). A carcinoma arising from either the exocervical squamous epithelium or the endocervical glandular epithelium. "Cervical carcinoma cells were rendered more susceptible to complement after treatment with blocking antibodies to CD59 and CD55, and lysis was increased further when cells were treated with both antibodies." (PMID 35227072, 2022). "Recently, CD59 has been reported to overexpress in the cervical cancers and in other cancers, while is low expressed in normal cells." (PMID 32185543, 2020). "IHC of CD59 was performed on cervical carcinomas, normal cervical epithelial cells, and the surrounding stroma." (PMID 28250389, 2014). "Notably, the level of CD59 within the tumor was strongly correlated with disease progression and survival in cervical cancer patients." (PMID 35606403, 2022). "Besides, CD59 was specific towards its receptor overexpressed in the cervical cancer cells that resulted in enhanced accumulation of liposomes and exhibited higher therapeutic effect." (PMID 32185543, 2020).
colon adenocarcinoma (5 papers, 2019 to 2024). "For example, TNFα and IL-1ß enhanced the expression of CD55 and CD59 in colon adenocarcinoma cells." (PMID 31024572, 2019).
melanoma (5 papers, 2017 to 2025). A malignant, usually aggressive tumor composed of atypical, neoplastic melanocytes. "5-azacytidine was shown to elevate the levels of CD55 and CD59 in Burkitt lymphoma cell lines but only of CD59 in melanoma cells." (PMID 31024572, 2019). "As for previous experiment, serial dilutions were coupled to beads and stained with anti-CD63 and anti-CD59 for melanoma-EVs or anti-CD63 and anti-MHC-I for T-lymphoblasts-EVs." (PMID 28900146, 2017). "A constitutive release of soluble CD59, which retains its activity as well as its GPI-anchor from human melanoma cells, was reported." (PMID 31024572, 2019). "These analyses revealed a good linear behaviour, with very high r2 values and p values < 0.001, in the range between 1 to 15 ng for melanoma-EVs using anti-CD63 and anti-CD59." (PMID 28900146, 2017). "Moreover, the rest of SASP-related genes recruited in our risk-scoring model including HLA-B, TPMT, ATM, CD59, TRIM21, and ASPRV1 have not been well studied in melanoma, indicating their potential of novel therapeutic target." (PMID 40864319, 2025).
neuromyelitis optica (5 papers, 2017 to 2025). A rare inflammatory disease of the central nervous system characterized mainly by attacks of uni- or bilateral optic neuritis (ON) and acute myelitis. "In model of neuromyelitis optica induced by passive administration of human IgG autoantibodies targeting aquaporin-4, rats deficient in the cell membrane inhibitor of complement activation CD59 showed a much more pronounced neurological pathology than CD59 KO mice (Yao and Verkman, 2017a,b)." (PMID 33959146, 2021). "Indeed, experimental rodents lacking CD59 display enhanced demyelination in both experimental autoimmune encephalomyelitis and the Aquaporin 4-IgG injection model of neuromyelitis optica, in agreement with the view that CD59-expression protects against complement-mediated degeneration." (PMID 33898427, 2021).
non-small cell lung carcinoma (5 papers, 2012 to 2025). A group of at least three distinct histological types of lung cancer, including non-small cell squamous cell carcinoma, adenocarcinoma, and large cell carcinoma. "An increased presence of the complement-inhibitory proteins CD55 and CD59 has been observed in non-small cell lung cancer (NSCLC) among various other malignancies, which has been associated with signaling from cytokines." (PMID 40515636, 2025). "Results have shown that in Herceptin treatment for non-small cell lung cancer (NSCLC), neutralization of CD55 and CD59 results in markedly increased Herceptin-mediated complement cytotoxicity." (PMID 31164885, 2019). "In non-small cell lung cancer (NSCLC) cells, CD55 and CD59 were closely correlated with histological types, prognosis and preoperational adjutant chemotherapy of the disease." (PMID 22634835, 2012).
thrombosis (5 papers, 2013 to 2025). "The proportion of CD59‐ neutrophils in the patients with thrombosis (11 cases) was (88.71 ± 9.499)%, which was significantly higher than those without thrombosis (58.28 ± 24.27)% (P = .0028)." (PMID 31502726, 2020). "We were particularly interested to investigate whether a potential CD59 defect in erythrocytes of PMM2-CDG patients might contribute to their increased incidence of thrombosis." (PMID 24139637, 2013). "Serum determination of antiphospholipid antibodies (anticardiolipin and anti-beta 2 glycoprotein antibodies), molecular testing, and CD55 and CD59 flow cytometry are not affected by acute thrombosis or anticoagulant treatment." (PMID 40150064, 2025).
breast tumors (4 papers, 2005 to 2023). "The opposite is true in breast tumors however, where loss of CD59 expression in breast tumors correlates with poor patient survival." (PMID 31164885, 2019). "However, it has also been shown that the loss of CD59 expression in breast tumors correlates with poor patient survival." (PMID 37371512, 2023).
Burkitt lymphoma (4 papers, 2015 to 2022). A rare form of malignant mature B-cell non-Hodgkin lymphoma. "These Abs were able to recognize CD20 expressed on Burkitt's lymphoma cell lines and to neutralize membrane-bound CD55 and CD59 enhancing cell susceptibility to C-mediated lysis." (PMID 30319647, 2018). "We permanently transfected Daudi cells (PIG-Y-deficient human Burkitt's lymphoma cell line) with wild-type (WT) or p.Leu46Pro mutant vector constructs driven by the weak promoter followed by assessment of cell surface expression of CD55 and CD59 by FACS analysis." (PMID 26293662, 2015). "Three Burkitt’s lymphomas; Raji, Daudi, and BJAB, and one mantel cell lymphoma; GRANTA-519 were cultured in 2D and the expression levels of CD20 and CD59 were analyzed by flow cytometry." (PMID 35725455, 2022).
chronic lymphocytic leukemia (4 papers, 2019 to 2022). "Furthermore, an increased expression level of inhibitory membrane-bound complement regulatory protein (mCRP) CD59 has been associated with rituximab resistance in chronic lymphocytic leukemia (CLL) patients." (PMID 36119088, 2022). "In addition, augmented expression of the inhibitory membrane-bound complement regulatory protein (mCRP) CD59 has been related to rituximab resistance in chronic lymphocytic leukemia (CLL) patients." (PMID 33212776, 2020).
glioblastoma (4 papers, 2017 to 2024). The most malignant astrocytic tumor (WHO grade IV). "Nine proteins, i.e., tubulin 2B chain, CD59, far upstream element-binding, CD44, histone H1.4, caldesmon, osteopontin, tropomyosin chain and metallothionein-2, marked the core of newly diagnosed glioblastoma with respect to tumor periphery." (PMID 33374813, 2020). "CD59 mRNA transcription analysis reveals that multiple cancers, such as diffuse large B cell lymphoma (DLBC), glioblastoma multiforme (GBM), pancreatic adenocarcinoma (PAAD), skin cutaneous melanoma (SKCM), and thymoma (THYM) exhibit significantly higher mRNA expression of CD59." (PMID 39518137, 2024).
glioma (4 papers, 2020 to 2023). A benign or malignant brain and spinal cord tumor that arises from glial cells (astrocytes, oligodendrocytes, ependymal cells). "Similar to the case of glioma, malignant prostate cells have been shown to overexpress CD59 in vitro." (PMID 34671342, 2021). "Of the three factors, CD59 is critical for the protection of human U87 and U251 glioma cell lines and selected patient GBM cell lines from complement attack." (PMID 34502484, 2021). "Expression of CD55 and CD59 could theoretically inhibit complement activation at the surface of growing GBM tumors in vivo, and CD59 overexpression has been observed in human glioma samples." (PMID 34671342, 2021).
hemolysis (4 papers, 2017 to 2025). Disruption of the integrity of the erythrocyte membrane causing release of hemoglobin. "The loss of CD59 especially leads to 'paroxysms' of acute intravascular hemolysis during events of stress." (PMID 32724752, 2020). "First, patients who experience red cell hemolysis after transfusions, despite no changes in commonly suspected blood group antigens, could be tested for the presence of CD59 variants." (PMID 40739794, 2025). "The lack of the complement regulators CD55 and CD59 on PNH erythrocytes accounts for the hallmark of PNH, which is the chronic, complement‐mediated intravascular hemolysis." (PMID 36110036, 2023).
hepatoma (4 papers, 2016 to 2025). "Previous studies observed a cytokine-mediated upregulation of CD55 and CD59 expression in human hepatoma cells in tumors mediated via pro-inflammatory cytokines such as tumor necrosis factor-alpha, IL-1 beta, and IL-6." (PMID 40723265, 2025). "A previous study had reported that HBV by up-regulating the complement regulatory protein CD59 in hepatoma cells restricts the functional MAC assembly and complement-dependent cytotoxicity." (PMID 36376872, 2022). "Given that HBx-elevated CD59 depressed the growth of hepatoma cells through protection of hepatoma cells from complement attack." (PMID 27050367, 2016). "We previously showed that HBx protected hepatoma cells from complement attack by activation of CD59." (PMID 27050367, 2016). "We previously reported that HBx activated CD59 in protection of hepatoma cells from complement attack." (PMID 27050367, 2016). "We previously found that HBx increased the complement regulation proteins such as CD46 and CD59 to protect hepatoma cells from complement attack." (PMID 27050367, 2016). "Interestingly, we showed that HBx up-regulated CD59 and or CD46 to inhibit complement activation and protected hepatoma cells from complement attack in the development of HCC." (PMID 27050367, 2016).
lymphopenia (4 papers, 2012 to 2014). Reduction in the number of lymphocytes. "However, diminished expression of CD55 and/or CD59 leading to enhanced susceptibility to complement-mediated lysis might also have caused lymphopenia." (PMID 25330534, 2014). "Diminished expression of CD55 and/or CD59 was previously reported in SLE patients with lymphopenia and hemolytic anemia." (PMID 25330534, 2014). "Another contributing factor to lymphopenia involves defective CD95/Fas systems and diminished expression of complement regulatory proteins (CD55 and CD59)." (PMID 24860837, 2014). "Compared with healthy controls, we observed in SLE patients with lymphopenia and neutropenia decreased expression of CD55, CD59, and CD46 (P < 0.05)." (PMID 22761633, 2012). "In a follow-up study an analysis of 40 SLE patients with and without lymphopenia showed that mean fluorescence intensities (MFI) of CD55 and CD59 were diminished on T- and B-cells in lymphopenic patients compared to nonlymphopenic patients." (PMID 24592327, 2014).
malaria (4 papers, 2011 to 2019). Malaria is a serious and sometimes fatal disease caused by a parasite that commonly infects a certain type of mosquito which feeds on humans. "Apparently, this is the first study to show variations in CD55 and CD59 levels in relation to RBC age during malaria." (PMID 22206234, 2011). "Our study highlights that the loss of CRPs in both species of malaria is particularly apparent in uninfected RBCs, whereas infected RBCs of both P. falciparum and P. vivax malaria have higher expression of CR1, CD55, and CD59 than uninfected RBCs." (PMID 30429373, 2018). "A loss of CD59 function is causally involved in hemolytic anemia in PNH, HIV and malaria." (PMID 24086391, 2013). "Patients with mild P. falciparum and P. vivax malarial anaemia also had lower CR1 (p = 0.055) and CD59 (p = 0.053) on reticulocytes compared to non-anaemic malaria patients, respectively." (PMID 31533836, 2019). "Although levels of other surface molecules are known to vary as RBC age, changes in the CD55 and CD59 levels in relation to cell aging during malaria have not been examined." (PMID 22206234, 2011). "CD59 levels were low during malaria compared to normal controls but the differences were not significant for all RBC subsets." (PMID 22206234, 2011). "Overall levels of CD55 but not CD59 were higher in the healthy controls than in other groups but this difference was only significant for the anaemic malaria cases." (PMID 22206234, 2011).
non-Hodgkin lymphoma (4 papers, 2014 to 2026). Distinct from Hodgkin lymphoma both morphologically and biologically, non-Hodgkin lymphoma (NHL) is characterized by the absence of Reed-Sternberg cells, can occur at any age, and usually presents as a localized or generalized lymphadenopathy associated with fever and weight loss. "Similarly, the use of mAbs blocking CD55 and CD59 in addition to Rituximab treatment leads to increased tumor toxicity in non-Hodgkin’s lymphoma." (PMID 33614473, 2020). "Similar findings were reported in an earlier study where lymphoid cells especially non-Hodgkin’s lymphoma cells, were reported to lack CD55, although, in most cases, another phosphatidyl inositol-anchored protein, CD59, was still present." (PMID 41526546, 2026).
polyneuropathy (4 papers, 2019 to 2024). A disease or disorder affecting more than one nerve. "Mutated CD59 has a higher susceptibility to glycation than the wild-type receptor, especially under hyperglycemic conditions, and inherent CD59 deficiency might lead to an early-onset haemolytic phenotype causing angiopathy and polyneuropathy." (PMID 39518935, 2024). "Mutations in CD59 cause CIDP-like polyneuropathy in children with inherited chronic hemolysis." (PMID 30794663, 2019).
rheumatoid arthritis (4 papers, 2006 to 2025). A chronic, systemic autoimmune disorder characterized by inflammation in the synovial membranes and articular surfaces. "Atorvastatin has also been reported to cause CD59 upregulation in hypoxia in a model of rheumatoid arthritis by a mechanism involving nitric oxide-dependent GGTase inhibition." (PMID 30851734, 2019). "In rheumatoid arthritis (RA), the CRIg-CD59 complement is encapsulated by ZIF-8 nanoparticles and forms a ZIF8@CRIg-CD59@HA@ZA complex with hydroxyapatite (HA) and zoledronic acid (ZA)." (PMID 40574069, 2025). "Regulation of complement inhibitors (CD55, CD35, CD59, and CD46) is important in autoantibody-mediated complement activation and is impaired in autoimmune diseases such as SLE, rheumatoid arthritis, and bullous pemphigoid." (PMID 30473747, 2018).
Sepsis (4 papers, 2022 to 2025). Sepsis is defined as life-threatening organ dysfunction caused by a dysregulated host response to infection. "Increased CD59 cell surface expression levels are associated with the development of sepsis." (PMID 40788542, 2025). "CD59 has also emerged as a potential guardian against muscle tissue damage during sepsis, implicating its role in the complement system and immune response dysregulation contributing to sepsis pathogenesis." (PMID 38348451, 2024). "Soluble CD59 (sCD59) levels correlate with organ damage severity in sepsis patients, with elevated levels observed, particularly post-48 h intensive care unit admission." (PMID 38348451, 2024). "Activation of the complement system is enhanced during sepsis and RBCs are protected by membrane surface proteins like CD35, CD55 and CD59." (PMID 35966861, 2022). "In addition, CD59, SERPINB2, CFD, and P2RX1 can be potential biomarkers for sepsis diagnosis." (PMID 41285832, 2025).
Stroke (4 papers, 2014 to 2025). Sudden impairment of blood flow to a part of the brain due to occlusion or rupture of an artery to the brain. "CD59 deficiency should be considered in infants with unexplained hypotonia, stroke, and hemolytic anemia." (PMID 40519381, 2025). "When restricting to participants without prevalent stroke in a sensitivity analysis, the significant proteins remained similar for gait speed decline, although follistatin‐related protein 3 and CD59 no longer reached the threshold for significance." (PMID 36333824, 2022). "Deficiency of CD59, an inhibitor of MAC (a pore-forming complex that mediates cell lysis), increased infarct volumes, brain swelling, and greater neurological deficits in a model of mild stroke but not in a model of severe stroke in mice." (PMID 33925147, 2021).
aplastic anemia (3 papers, 2016 to 2025). Anemia resulting from bone marrow failure (aplastic or hypoplastic bone marrow). "A small Egyptian study found that, among 11 newly diagnosed treatment-naïve pediatric patients with aplastic anemia who were screened for PNH by immunohistochemical bone marrow staining using CD59 monoclonal antibody, four (36%) had PNH clones." (PMID 40886199, 2025).